CASC9 (cancer susceptibility 9)
Diseases named in the same sentence as CASC9 in open-access papers (continued):
Sharing a sentence is not in itself a finding about the gene and the disease.
tumor (continued). "RT-qPCR was performed to analyze CASC9 expression in 35 cases of OSCC tissues and paired para-tumor tissues." (PMID 30674868, 2019). "Data mining revealed prominently CASC9, a lncRNA significantly overexpressed in HNSCC tumor tissues according to the TCGA RNAseq data." (PMID 31412811, 2019). "Etiology of the chronic liver disease, histopathological grading, tumor nodularity, size, AFP serum levels and time-to-recurrence (TTR) after surgery were tested against LUCAT1, CASC9 and LINC01093 expression." (PMID 30416681, 2018). "Remarkably, serum CASC9 levels directly correlated with HCC nodule size (Pearson's correlation 0.54, p=0.04) indirectly supporting their secretion from tumor mass into the bloodstream." (PMID 30416681, 2018). "We next divided 91 ESCC tissues into two groups according to CASC9 expression level and compared ESCC tumor size and TNM stage." (PMID 28854977, 2017). "Following qRT-PCR results suggested that lncRNA CASC9 expression is elevated in most ESCC tissues, especially in advanced samples with larger tumor size, and its higher expression predicts a poor clinical outcome." (PMID 28854977, 2017). "AC093895.1, CASC9, HOXC-AS2, and LINC01980 may be involved in tumor progression, and the molecular mechanism remains to be further verified." (PMID 36445051, 2023). "Data from qRT-PCR showed that the expression of CASC9 in OS tumor groups was memorably higher than that in the normal groups (P = 0.0156)." (PMID 36266695, 2022). "Some studies found that as a competing endogenous RNA, CASC9 inhibits miRNA expression by competitively binding to its target miRNA at the 3′UTR region via a sponging effect and then regulates the progression of various human neoplasms." (PMID 35427373, 2022). "WGCNA and Kaplan-Meier survival analysis revealed that 5 DELs (MIR4435-2 HG, CASC9, LINC01980, STARD4-AS1 and MIR99AHG) were significantly correlated with OS of HNSCC patients, whereas DEL PART1 was most significantly correlated with the HNSCC tumor." (PMID 34898376, 2021). "CASC9 upregulation is significantly positively correlated with BCa tumor invasion depth, histological grade, and age; however, sex and tumor volume were not related to CASC9 expression levels." (PMID 34611133, 2021). "Further analysis revealed that tumor differentiation grade, primary tumor invasion depth, lymph node metastasis, and advanced TNM stage were all positively correlated with CASC9 expression, which strongly suggested that CASC9 might contribute to ESCC malignance, particularly metastasis." (PMID 29511340, 2018). "However, since experimental modulation of CASC9 expression in HNSCC cell lines did not appear to exert a major influence on tumor cell properties in vitro, CASC9 may not be crucially involved in the establishment of the neoplastic phenotype in all HNSCC tumors, but may reflect the transformed state." (PMID 31412811, 2019).
cancer (42 papers, 2014 to 2025). A tumor composed of atypical neoplastic, often pleomorphic cells that invade other tissues. "Cancer susceptibility 9 (CASC9) a lncRNA called CASC9 has been connected to the emergence and spread of cancer." (PMID 38522008, 2024). "ASO-mediated linc00210 absence inhibits HCC cell self-renewal and aggression, but knockout of lncRNA CASC9 (cancer susceptibility candidate 9) by RNAi decreases cancer progression in HCC." (PMID 36004931, 2022). "Although previous studies have found that cancer susceptibility candidate 9 (CASC9) highly expresses in NPC, the underlying mechanisms need to be further studied." (PMID 35419295, 2022). "Cancer susceptibility candidate 9 (CASC9) is a conserved lncRNA with 1500 nucleotides (nt) in length." (PMID 36266695, 2022). "In this study, we investigated how the cancer susceptibility candidate 9 (CASC9) gene affects the cell growth, invasion, migration, and apoptosis of BC cells." (PMID 34711117, 2021). "Here, our research paid close attention to the coordination within m6A and lncRNA CASC9 (cancer susceptibility 9) based on the MeRIP-Seq (methylated RNA immunoprecipitation sequencing) in GBM." (PMID 34645788, 2021). "It has been suggested that CASC9 is a novel diagnostic, prognostic, and therapeutic target in cancer treatment." (PMID 34017854, 2021). "Cancer susceptibility candidate 9 (CASC9) is an lncRNA that has been reported in many cancers, but its role in CRC is poorly understood." (PMID 34017854, 2021). "Cancer susceptibility candidate 9 (CASC9), a recently discovered lncRNA, consists of four transcript variants CASC9-201, CASC9-202, CASC9-203, and CASC9-204." (PMID 34017854, 2021). "Cancer susceptibility candidate 9 (CASC9, Gene ID 101805492 in NCBI records) is a novel identified lncRNA located at 8q21.11." (PMID 32677984, 2020). "Cancer susceptibility candidate 9 (CASC9, Gene ID 101805492 in NCBI records), which is the most up-regulated lncRNA in ESCC (GSE89102,fold change = 355.82385, p = 3.52E-06), predicts poor prognosis of ESCC." (PMID 28854977, 2017). "Of which, CASC9 (Homo sapiens cancer susceptibility candidate 9, LINC00981) has been recently validated in other cohorts of ESCC patients and reported to play the oncogenic roles in ESCC." (PMID 26158411, 2015). "Cancer susceptibility candidate 9 (CASC9) plays a critical role in varieties of human cancers." (PMID 35578597, 2022). "CASC9 earned significant attention of researchers because of the potential roles of its transcript variants in association with the pathogenesis of various cancer." (PMID 34017854, 2021). "CASC9 expression levels were also associated with cancer pathological stages." (PMID 33050576, 2020). "LncRNA CASC9 was firstly reported in esophageal squamous cell carcinoma as an oncogene in 2015, and was subsequently confirmed to be associated with tumorigenesis and progression of malignant tumors including gastric cancer, hepatocellular carcinoma and breast cancer." (PMID 35419295, 2022). "Recently, in OSCC, another lncRNA CASC9 was found to promote cancer progression through suppressing autophagy-mediated cell apoptosis via inducing AKT phosphorylation and the subsequent activation of the AKT/mTOR pathway." (PMID 35898889, 2022). "A meta-analysis had evaluated the impact of CASC9 on the prognosis and clinicopathological features of patients with cancer, found that a higher CASC9 signified a severe invasion, and high CASC9 meant lower overall survival rate." (PMID 35427373, 2022). "LncRNA CASC9 of carcinomas significantly expressed more highly than that of para-cancerous tissues in CRC patients (p<0.01)." (PMID 35427373, 2022). "In recent years, a growing number of studies have shown that CASC9 is overexpressed in various cancers, contributing to the progression of cancer cells." (PMID 33298846, 2020).
cancer (continued). "Subsequent studies have shown that CASC9 promotes the progression of many other cancers, such as hepatocellular carcinoma, oral squamous cell carcinoma, CRC, and ovarian cancer." (PMID 33298846, 2020). "CASC9 was significantly overexpressed in cancers of various organs including bladder, liver, stomach and lung." (PMID 31412811, 2019). "Taken together, these findings demonstrate for the first time that CASC9, which is highly expressed in cancer cells, inhibits autophagy by activating the AKT/mTOR pathway." (PMID 30674868, 2019). "As a prerequisite for studying CASC9 function in HNSCC, we investigated CASC9 expression in cell lines from different cancer types by RT-qPCR." (PMID 31412811, 2019). "The ECM–receptor interactions and focal adhesion pathways consist of many well-known genes functioning in cell motility and cancer metastasis, which is consistent with the pro-metastatic role of CASC9." (PMID 29511340, 2018). "It was subsequently determined that CASC9 was overexpressed in many cancer types and promoted cell proliferation, differentiation, and invasion." (PMID 29511340, 2018). "We selected two upregulated lncRNAs (LINC00152 and CASC9) that were reported to be upregulated in other cancers, and two mostly downregulated lncRNAs (LINC00226 and F11‐AS1) for further validation in PDAC cell lines and the normal cell line HPDE." (PMID 28220683, 2017). "A comparison of CASC9 expression in ESCC cell lines and other common cancers cells revealed that CASC9 was specifically up-regulated in ESCC cells." (PMID 28854977, 2017). "Compared with other cancer cells, CASC9 is specifically highly expressed in ESCC cells, which indicates that the expression of CASC9 is relatively tissues-specific." (PMID 28854977, 2017). "Then, quantitative reverse transcriptase PCR (qRT‐PCR) was performed to investigate the expression of CASC9 in 44 cancer tissues and five ESCC cell lines." (PMID 27431358, 2016). "Our findings are in line with previous articles in CRC and other cancers and hence leading us to hypothesize that CASC9 may be involved in specific pathogenesis of CRC carcinogenesis." (PMID 34017854, 2021). "From the GEPIA database, lncRNA CASC9 was upregulated in multiple cancer types." (PMID 34612783, 2021). "We first interrogated CASC9 expression in 42 pairs of BC and non-carcinoma tissues by qRT-PCR." (PMID 34711117, 2021). "Cancer susceptibility candidate 9 (CASC9) is a novel long non-coding RNA and plays important regulatory role in diverse biological processes of cancers." (PMID 32677984, 2020). "It is unclear whether the increased CASC9 expression in cancer cells regulates the expression of mTOR through the regulation of the PI3K/AKT signaling pathway to control autophagy." (PMID 30674868, 2019). "We further performed an in silico analysis of CASC9 expression in public pan-cancer TCGA data." (PMID 31412811, 2019). "Recently, lncRNA CASC9 was shown to be dysregulated in many cancer types, but the mechanisms whereby this occurs remain largely unknown." (PMID 29511340, 2018). "First we detected the expression of CASC9 in some common cancer cells." (PMID 28854977, 2017). "CASC9 has been implicated in HNSCC, where it is often upregulated and hence, CASC9 overexpression might aid in the migration, multiplication, and spread of cancer cells." (PMID 38522008, 2024). "Moreover, elevated CASC9 expression in OSCC may play a role in promoting cancer by activating the AKT/mTOR signaling pathway to regulate autophagy." (PMID 30674868, 2019). "CASC9 was found to activate mTOR-dependent autophagy and EMT pathway activity in CRC to promote cancer progression." (PMID 40746360, 2025). "CASC9, POU3F3, SNHG3, CDKN2B-AS1, and ZEB2-AS1 are predicted to sponge several miRNAs (in cancer cells) to promote cancer proliferation." (PMID 37190145, 2023).
cancer (continued). "LAMC2 and CASC9 have been shown to be important biomarkers for metastasis therapy and the prognosis of ESCC, confirming the potential for HTML to play a role in cancer diagnosis and treatment." (PMID 37889117, 2023). "To comprehensively understand these four lncRNAs (LINC01224, CASC9, LINC00346, and TRPM2-AS) and seven target mRNAs (CCNF, PKMYT1, GCH1, TK1, PSAT1, ADAM33, and DDX11), we performed genome instability, immune, cancer stemness, and drug sensitivity analysis." (PMID 34368141, 2021). "Combined overexpression of CASC9 and HOTAIR in the DUS set discriminated perfectly between normal and cancerous tissues, but detected fewer cancer samples." (PMID 31412811, 2019). "We validated CASC9 overexpression in two independent HNSCC tissue sets by RT-qPCR and further investigated CASC9 expression in various other cancers." (PMID 31412811, 2019). "Similar to CASC9, PVT1 discovered earlier can promote the occurrence and progression of cancer." (PMID 33585468, 2020). "Previous evidences outlined the exosome-mediated secretion of lncRNAs and their detection in serum of cancer patients, thus we tested HCC derived cell lines for CASC9 and LUCAT1 expression in the intra and extracellular compartment, as well as in the exosomal fraction of cell culture supernatant." (PMID 30416681, 2018). "Our data suggest that although CASC9 is an excellent indicator of cancer in the oropharyngeal tract, it may not be crucially involved in the establishment of the neoplastic phenotype in all cases." (PMID 31412811, 2019). "However, CASC9 expression was undetectable in all these cell types (data not shown), demonstrating exclusive cancer cell-specific expression." (PMID 31412811, 2019).
CASC9 also shares sentences with these, for which no sentence is quoted: papillary thyroid cancer (4 papers); osteosarcoma (2); cardiovascular system disorder (1); hemangioma (1); metabolic disease (1); oesophageal cancer (1); rectal cancer (1); renal cell carcinoma (1); retinoblastoma (1); stomach cancers (1).